PDGFRB (platelet derived growth factor receptor beta)
Diseases named in the same sentence as PDGFRB in open-access papers (continued):
Sharing a sentence is not in itself a finding about the gene and the disease.
Obesity (13 papers, 2013 to 2025). Accumulation of substantial excess body fat. "In multiple strains of mouse models, alterations in the frequency of PDGFRβ + cell subpopulations have been linked to adipose tissue remodeling during diet-induced obesity, serving as an indicator of metabolic status of WAT." (PMID 38509584, 2024). "Hence, we next set to determine whether PDGFRβ + cell HIF2α inactivation would be associated with changes of hepatic fat content and systemic metabolism in the setting of obesity." (PMID 38509584, 2024). "The present study revealed a critical role for PDGF-BB/PDGFRβ signaling in pericytes in the development of chronic inflammation in the hypothalamus during the early stage of obesity." (PMID 38317079, 2024). "In conclusion, PDGFRβ signaling in hypothalamic pericytes promoted microglial polarization and contributed to the progression of the obesity pathology." (PMID 38317079, 2024). "Further experimentation into if and how Pdgfrβ expression and signaling becomes augmented during obesity to influence beige fat development remains unrealized." (PMID 37002214, 2023). "An exception is WAT, in which PDGFRβ ASC depletion with the TK suicide gene prevents obesity development." (PMID 34680151, 2021). "Similar results were reported in a model of tamoxifen-inducible systemic PDGFRβ ablation in diet-induced obesity." (PMID 34359916, 2021). "To determine the potential for complement inhibition to prevent cerebrovascular damage in obesity, we first assessed pericytes number using PDGFRβ immunoreactivity." (PMID 32273396, 2020). "Increasing the adipogenic capacity of Pdgfrβ+ precursors through Pparg overexpression results in healthy visceral WAT expansion in obesity and adiponectin-dependent improvements in glucose homeostasis." (PMID 29497032, 2018). "PDGF-BB/PDGFRβ signalling is associated with obesity and metabolic dysfunction, and PDGFRα activation was shown to switch APC plasticity towards a profibrotic phenotype, and led to obesity-induced WAT fibrosis." (PMID 34714716, 2021). "Here, we test the hypothesis that the potential to recruit new adipocytes from Pdgfrβ+ preadipocytes determines visceral WAT health in obesity." (PMID 29497032, 2018). "In addition, PDGF-β/PDGFRβ signaling plays a unique and essential role in the initiation of adipose tissue angiogenesis responding to tissue expansion during the development of obesity." (PMID 35454174, 2022). "Collectively, the data in this study support that PDGFRβ + cell HIF2α is dispensable for WAT metabolic remodeling and the consequential effects on liver and systemic metabolic homeostasis in diet-induced obesity." (PMID 38509584, 2024). "Suppression of HIF1α in PDGFRβ + progenitors promotes adipogenesis within subcutaneous and intra-abdominal depots, leading to healthy WAT remodeling and improved metabolic health in obesity." (PMID 38509584, 2024). "Here, a TAM-inducible model of PDGFRβ + cell specific HIF2α inactivation was utilized to determine the regulatory role of HIF2α in controlling adipose progenitor function and WAT metabolic remodeling in the context of diet-induced obesity." (PMID 38509584, 2024).
pulmonary hypertension (13 papers, 2011 to 2024). Increased pressure within the pulmonary circulation due to lung or heart disorder. "In the hypoxia-induced pulmonary arterial hypertension model, IMA inhibited the perivascular fibrosis via blocking PDGFRβ pathway." (PMID 28570599, 2017). "Many genes are functionally related to high-altitude physiology, such as angiogenesis (RGCC), pulmonary hypertension remodeling (PLA2G12A), oxygen intake (C9ORF3), neural response (GRID1 and GRIN2B), melanin synthesis (MITF, PDGFRB and PIK3R3) and heart development (FOXS1, GAA and MYLK2)." (PMID 25270331, 2014).
breast tumors (12 papers, 2014 to 2025). "Furthermore, PDGF signaling has been found to play an active role in breast tumor progression and PDGFRB has previously been theorized—along with its cognate ligand PDGFB—to be a potential therapeutic target for multiple human cancers, including breast." (PMID 37200395, 2023). "With exception of SNAI3, all the up-regulated genes are known to be involved in breast tumor malignancy and include the transcription factor FOXC2, PDGFRB and members of the WNT family, whose products are known to sustain the metastatic process of breast tumors." (PMID 24962430, 2014).
cholangiocarcinoma (12 papers, 2010 to 2026). A carcinoma that arises from the intrahepatic biliary tree (intrahepatic cholangiocarcinoma) or from the junction, or adjacent to the junction, of the right and left hepatic ducts (hilar cholangiocarcinoma). "PDGFD can also bind PDGFRB and activate cancer-associated fibroblasts (CAFs) that play crucial roles in modulating cholangiocarcinoma development." (PMID 37838792, 2023). "However, growth factor signaling (EGFR, PDGFRβ) and downstream effectors (MAPK pathway) are more active in cholangiocarcinoma organoids and could provide potential druggable targets." (PMID 35764936, 2022).
chronic myelomonocytic leukemia (12 papers, 2006 to 2024). A myelodysplastic/myeloproliferative neoplasm which is characterized by persistent monocytosis, absence of a Philadelphia chromosome and BCR/ABL fusion gene, fewer than 20 percent blasts in the bone marrow and blood, myelodysplasia, and absence of PDGFRA or PDGFRB rearrangement. "Previous case reports involving PDGFRB mutations have described features similar to chronic myelomonocytic leukemia, chronic eosinophilic leukemia, or mastocytosis." (PMID 23936692, 2013). "PDGFRB-rearranged cases preferentially manifest as chronic myelomonocytic leukemia (CMML), and less frequently as CEL, MPN or atypical chronic myeloid leukemia (aCML)." (PMID 34205834, 2021). "In contrast to rearrangements involving PDGFRB, the FIP1L1- PDGFRA rearrangement is exceedingly rare in the setting of chronic myelomonocytic leukemia." (PMID 24669761, 2014).
metastatic disease (12 papers, 2008 to 2024). "The controversy regarding the roles of PDGFRα and PDGFRβ in MB has continued, i.e., PDGFRα was deregulated in both the primary and metastatic tumors in a sleeping beauty mouse model of MB." (PMID 25576913, 2015). "Furthermore, several in vivo as well as clinical studies have also indicated that PDGFRB as a potential therapeutic target for metastatic disease." (PMID 24626295, 2014). "Two markers of stromal tumor response (PDGFRB, SPARC) showed marked differential expression between primary ovarian and metastatic tumor samples." (PMID 24204986, 2013).
brain tumors (11 papers, 2014 to 2025). "In addition, the transcripts of two markers linked to brain tumor proliferation, PDGFR-β (platelet-derived growth factor receptor beta), and Ki-67 were also significantly decreased." (PMID 33585565, 2020).
Cerebral ischemia (11 papers, 2015 to 2025). Restriction of arterial blood supply to the brain associated with insufficient oxygenation to support the metabolic requirements of the tissue. "Additionally, PDGFRβ signaling plays a crucial role in stabilizing blood vessels; inhibition of PDGFRβ signaling has been associated with increased B-BB permeability and aggravated brain edema in a mouse model of cerebral ischemia." (PMID 40671131, 2025). "For instance, PDGFR-α activation contributes to B-BB impairment via p38 MAPK in intracerebral hemorrhage, while PDGFRβ inhibition increases B-BB permeability and exacerbates brain edema in cerebral ischemia." (PMID 40671131, 2025). "To study the possible occurrence of pericyte apoptosis during I/R injury as observed in cerebral ischemia, we stained 30 min, 60 min, and 24 h serial sections for PDGFRβ and for the active form of Caspase 3 (Casp3)." (PMID 29875766, 2018). "The expression of PDGFRβ is increased after cerebral ischemia." (PMID 31740626, 2019). "The data from this study demonstrated that upon I/R injury, treatment with SAL, PNS, or both increased the expression of PDGFRβ, which suggested that treatment with SAL and PNS targeted at preventing pericyte death was beneficial to the maintenance of BBB function after cerebral ischemia." (PMID 39295106, 2024). "The binding of PDGF to PDGFRβ by activating the PI3K-Akt signaling pathway in rat models can enhance cell proliferation and migration, promoting early vascular repair and angiogenesis after cerebral ischemia–reperfusion injury." (PMID 36909944, 2023). "We speculate that Dl-3-n-butylphthalide has a neuroprotective effect on focal cerebral ischemia/reperfusion, which may be mediated through ferroptosis-dependent SLC7A11/GSH/GPX4 signal pathway and PDGFRβ/PI3/Akt signal pathway." (PMID 36909944, 2023). "In this study, we built a model of brain ischemia–reperfusion to observe whether the SLC7A11/GSH/GPX4 and PDGFRβ/PIK/Akt signal pathways were involved in the process; most importantly, we evaluated whether these two pathways could be potential valid targets of DL-NBP treatment." (PMID 36909944, 2023).
cervical carcinoma (11 papers, 2006 to 2025). A carcinoma arising from either the exocervical squamous epithelium or the endocervical glandular epithelium. "We found that CAF markers, such as fibroblast activation protein (FAP), ACTA2 (α-SMA), and beta-type platelet-derived growth factor receptor (PDGFRB) were associated with the infiltration of macrophages in cervical cancer in the Tumor Immune Estimation Resource (TIMER) database." (PMID 36900416, 2023). "PDGFRβ in CAFs can interact with PDGF-BB expressed by cervical cancer cells and promote cancer cell growth by upregulating the expression of heparin-binding epidermal growth factor (HB-EGF) and activating the EGFR signaling pathway." (PMID 37143134, 2023). "There is a single study showing that the four primary cervical cancers analyzed by immunohistochemistry expressed the PDGFRβ." (PMID 17014709, 2006). "We postulate that this mode of action might be maintained in other tumors expressing elevated PDGFRβ levels such as cervical cancer and castration-resistant prostrate cancer." (PMID 36045346, 2022).
liver disease (11 papers, 2011 to 2025). "Circulating platelet-derived growth factor receptor-β (PDGFRβ) has recently been found to correlate with severity of liver disease in multiple etiologies, including liver steatosis." (PMID 40676525, 2025). "Apelin has been shown to increase the synthesis of collagen I and platelet-derived growth factor receptor β (PDGFRβ) in LX-2 cells, indicating that apelin may be an important mediator of fibrosis in human liver disease." (PMID 39744169, 2025). "Therefore, this study investigated the time- and dose-dependent effect of Y27 with HSA modified with PDGFRβ-recognizing peptides (Y27pPBHSA) on portal hypertension and renal perfusion in cirrhotic rats." (PMID 30783172, 2019). "In addition, and consistent with the notion that PDGFRα regulates the liver’s response to injury, patients with liver disease have elevated expression of PDGFRα and PDGFRβ." (PMID 24667490, 2014).
myocardial infarction (11 papers, 2013 to 2025). Gross necrosis of the myocardium, as a result of interruption of the blood supply to the area, as in coronary thrombosis. "For example, responses to myocardial infarction were differentially modulated by antibodies against PDGFRβ (inhibition of vascular maturation) or PDGFRα (decreased collagen deposition)." (PMID 27513343, 2016). "However, after myocardial infarction (MI), Pdpn is upregulated in a heterogeneous cell population such as PDGFRα-, PDGFRβ-, and CD34-positive cells, besides lymphatic endothelial cells." (PMID 36970507, 2023). "The development of [68Ga]Ga-ATH001, a PDGFRβ-targeted Affibody molecule-based PET tracer, addresses an unmet clinical need for non-invasive imaging of active fibrogenesis in patients following myocardial infarction (MI)." (PMID 41471324, 2025). "BMMSC-sEV treatment could increase the level of platelet-derived growth factor receptor-β (PDGFRβ), an angiogenetic factor, more than BMMSC treatment itself within 24 h after myocardial infarction in rats." (PMID 36686710, 2022). "PDGFRβ was enriched in fibrotic areas, although its expression was increased by BMMSC-sEV treatment at 24 h, but it was reduced after 4 weeks of myocardial infarction, which may be the reason for the antifibrotic effects of sEVs." (PMID 36686710, 2022). "They found that the expression of PDGFA, PDGFD and PDGFRB in the infarcted myocardium were increased after myocardial infarction, whereas PDGFB and PDGFC mRNAs were reduced and protein levels at infarcted myocardium were all significantly reduced in the early stage of myocardial infarction." (PMID 39569832, 2024).
myofibromatosis (11 papers, 2017 to 2025). "PDGFRB variants of Tier IIC identified in a substrate of infantile myofibromatosis provided indications for imatinib, which afforded significant reduction in pathological foci and the elimination of a life-threatening lesion in the interventricular septum." (PMID 41373618, 2025). "The combination of PDGFRB p.W566R/p.Y589N variants warranted imatinib for advanced infantile myofibromatosis with the liver, intraventricular septum involvement and multiple bone lesions." (PMID 41373618, 2025). "At the molecular level, germline or somatic heterozygous mutations in PDGFRB have been identified as the underlying cause of infantile myofibromatosis." (PMID 39583463, 2024). "In recent years, a genetic component has been suggested to exist in the familial form of infantile myofibromatosis, due to autosomal dominant inheritance and mutations in the PDGFRB gene." (PMID 33464419, 2021). "The VEGF receptor inhibitor sunitinib has demonstrated its efficiency and safety profile in the treatment of a PDGFRB mutated myofibromatosis case." (PMID 33830670, 2021). "To date, several studies have confirmed a connection between the p.R561C mutation in gene encoding platelet-derived growth factor receptor beta (PDGFR-beta) and the development of infantile myofibromatosis." (PMID 30200486, 2018). "Herein, we report the case of a patient with refractory multiple infantile myofibromatosis who was confirmed to harbor the PDGFRB germline mutation and who responded well to treatment with the PDGFRβ tyrosine kinase inhibitor sunitinib." (PMID 28183292, 2017). "Moreover, in several families, the c.1681C>T (p.Arg561Cys) mutation in the PDGFRB gene was found to cause familial infantile myofibromatosis." (PMID 28183292, 2017). "In line with this hypothesis, it has previously been observed that elevated levels of PDGFRB have been noted in pediatric fibromatosis and myofibromatosis." (PMID 33509954, 2021).
clear cell renal cell carcinoma (10 papers, 2022 to 2025). "In colorectal cancer and clear cell renal cell carcinoma (ccRCC), lactylation is increased, which stimulates PDGFRβ signaling to advance the tumor." (PMID 39968078, 2025). "In clear cell renal cell carcinoma, histone lactylation promotes a Platelet Derived Growth Factor Receptor Beta (PDGFR-β)-mediated positive feedback loop that drives aggressive disease progression." (PMID 40806283, 2025). "In a series of 1423 RCC tissue specimens studied by Song et al16 (2014), cytoplasmic overexpression of PDGFRβ was detected in 32.8% of clear cell renal carcinomas." (PMID 40434293, 2025). "Clear cell renal cell carcinoma progression is driven by a positive feedback loop between PDGFRβ signaling and inactive VHL-triggered histone lactylation." (PMID 39968078, 2025). "Simultaneously, the significant efficacy of inhibiting histone lactylation and PDGFRβ signaling has been observed in clear cell renal cell carcinoma." (PMID 39010066, 2024). "Inactive von Hippel-Lindau (VHL) is an important factor in the pathogenesis of clear cell renal cell carcinoma (ccRCC), which exerts oncogenic effects by inducing histone lactylation to activate platelet-derived growth factor receptor beta (PDGFRβ) expression." (PMID 36686771, 2022). "In contrast, positive feedback often leads to excessive cell proliferation, a prominent example of which is tumor formation, as exemplified by the VHL–histone lactylation–PDGFRβ positive feedback loop that contributes to accelerating the progression of clear cell renal cell carcinoma." (PMID 41413918, 2025). "Inactive von Hippel-Lindau (VHL) was associated with metabolic reprogramming in clear cell renal cell carcinoma (ccRCC), and it was reported that carcinogenic positive feedback exists between histone lactylation caused by inactive VHL in ccRCC and platelet-derived growth factor receptor β (PDGFRβ)." (PMID 39502530, 2024). "Histone lactylation triggered by inactive VHL could contribute to ccRCC progression through activating the transcription of PDGFRβ, and PDGFRβ can stimulate glycolysis, lactic acid production and the increase of histone lactylation in clear renal cell cancer cells." (PMID 39502530, 2024). "For instance, in clear cell renal cell carcinoma, inactivation of VHL can trigger histone lactylation, activating the PDGFRβ signaling pathway, forming a positive feedback loop, and promoting tumor progression." (PMID 39010066, 2024).
Ewing sarcoma (10 papers, 2005 to 2025). A small round cell tumor that lacks morphologic, immunohistochemical, and electron microscopic evidence of neuroectodermal differentiation. "The platelet-derived growth factor receptor beta (PDGFRB) has been shown to contribute to Ewing sarcoma growth and metastasis in vitro and in vivo and demonstrated the most prominent activation upon plerixafor treatment in A673 CXCR4-low cells." (PMID 29776413, 2018). "In this manuscript we began to address these questions and our data as yet support feedback survival signaling between the CXCR4 chemokine receptor and the growth factor and RTK network, in Ewing sarcoma PDGFRB in particular, as a plausible mechanism." (PMID 29776413, 2018). "Among the several plerixafor-activated RTKs in Ewing sarcoma cell lines, PDGFRB demonstrated most pronounced activation in phospho-tyrosine arrays." (PMID 29776413, 2018). "CDKN1C and a related member of the FOXO family, FOXO1, have previously been shown to inhibit Ewing Sarcoma growth, while FOXM1, GLI1 and PDGFRB have been shown to be growth-promoting in Ewing Sarcoma." (PMID 30237855, 2018). "In addition, Wang and co-workers showed that PDGFRB inhibition alone reduces spontaneous growth and metastasis in Ewing Sarcoma (EWS)." (PMID 28435517, 2017). "However, PDGFRB inhibitors showed no more than limited clinical activity, possibly because activating mutations are rare in Ewing sarcoma." (PMID 29776413, 2018). "PDGFRB was identified as a candidate driver RTK and potential therapeutic co-target for CXCR4 in Ewing sarcoma." (PMID 29776413, 2018).
lung adenocarcinoma (10 papers, 2006 to 2023). A carcinoma that arises from the lung and is characterized by the presence of malignant glandular epithelial cells. "Importantly, in situ myCAFs (αSMA+ cells) and inflammatory iCAFs (PDGFRβ+ cells) are two distinct populations of CAFs that transcribe satDNA in human lung adenocarcinoma tissue." (PMID 36635266, 2023).
medulloblastoma (10 papers, 2009 to 2022). A malignant, invasive embryonal neoplasm arising from the cerebellum. "Importantly, both PDGFRα and c-Kit are upregulated in medulloblastoma, and PDGFRβ was shown to be critical for migration and invasion of medulloblastoma cells." (PMID 31539380, 2019). "Moreover, Abouantoun and co-workers showed PDGFRB tyrosine kinase activity is critical for migration and invasion of medulloblastoma cells, possibly by trans-activating EGFR, and thus its depletion may represent an important therapeutic strategy for the treatment of this cancer." (PMID 28435517, 2017). "We speculate that the activation of the downstream targets of PDGFRβ in the AD cells is due to cross-talk between this receptor and the neighboring EGFR, a finding we previously reported to occur in childhood medulloblastoma cells." (PMID 29298329, 2018).